LOXL1-AS1 (LOXL1 antisense RNA 1)
Gene: Long non-coding RNA gene on chromosome 15 (73,898,471 to 73,928,296, reverse strand). Ensembl gene ENSG00000261801.
Diseases named in the same sentence as LOXL1-AS1 in open-access papers:
LOXL1-AS1 is named in the same sentence as 8 diseases in open-access papers, as found by Europe PMC text mining. Sharing a sentence is not in itself a finding about the gene and the disease. The quoted sentences say what the papers report.
glioblastoma (1 paper, 2019). The most malignant astrocytic tumor (WHO grade IV). "lncRNA LOXL1 antisense RNA 1 (lncRNA LOXL1-AS1) was recently found to function as oncogenic lncRNA in glioblastoma, prostate cancer, and medulloblastoma." (PMID 30944201, 2019).
thymic carcinoma (1 paper, 2024). Thymic carcinoma (TC) is a type of thymic epithelial neoplasm characterized by a high malignant potential. "Therefore, the overexpression of HSPA9, resulting from the overexpression of LOXL1AS1, inhibits apoptosis and promotes proliferation and invasion in both thymoma and thymic carcinoma." (PMID 39136001, 2024). "There is a positive correlation between the expression levels of LOXL1AS1 and HSPA9, and there is a negative association between miR-525–5p and HSPA9 in thymoma and thymic carcinoma." (PMID 39136001, 2024).
LOXL1-AS1 also shares sentences with these, for which no sentence is quoted: cancer (1 paper); lung adenocarcinoma (1); medulloblastoma (1); prostate carcinoma (1); thymoma (1); tumor (1).